AQP5 (aquaporin 5)
Diseases named in the same sentence as AQP5 in open-access papers (continued):
Sharing a sentence is not in itself a finding about the gene and the disease.
cancer (continued). "Overall, several AQPs, including AQP1, AQP3, AQP4, AQP5, AQP8, and AQP9, have been suggested to transport H2O2, and their expression promotes cancer cell growth and migration, However, solid data exist only for AQP3- mediated H2O2 transport as one of the key mechanisms for cancer cell migration." (PMID 35847914, 2022). "In order to define AQP3 and AQP5 as targets for cancer treatment, it is needed to thoroughly study all possible aspects and pathways affected, as inadequate inhibition or stimulation of each AQP could drive cancer cells to the more malignant phenotype." (PMID 33947079, 2021). "ACC had low or no AQP3 and AQP5 expression when compared to normal tissues, which might be due to a downregulation of these proteins during de-differentiation and cancer development." (PMID 32630469, 2020). "We thus hypothesized that, in addition to water, human AQP5 may also channel H2O2, and that the high level of expression and peroxiporin activity may play a key role in cellular adaption to oxidative stress, with impact on cancer cell migration." (PMID 31277235, 2019). "Therefore, it is reasonable to hypothesize that AQP5 ability to permeate H2O2 in addition to water, could also contribute to its up-regulation in cancer tissues." (PMID 27983600, 2016). "Consequently, due to its involvement in cancer progression, we anticipated that AQP5 might also be able to facilitate H2O2 permeation and have a role in cell oxidative stress response explaining, at least in part, its overexpression in cancer tissues." (PMID 27983600, 2016). "However, the possibility that AQP5 may promote cancer cell migration by other mechanisms could not be excluded." (PMID 25217331, 2014). "Interestingly, unlike carcinoma cells where AQP5 shows membranous expression, in the bone marrows of CML patients, megakaryocytes, myeloblasts, and granulocytes demonstrated cytoplasmic expression of AQP5." (PMID 18612408, 2008).
infection (8 papers, 2009 to 2025). The state of being infected such as from the introduction of a foreign agent such as serum, vaccine, antigenic substance or organism. "The altered expression in Aqp1 and Aqp5 represents physiological and pathological changes in the lungs exposed to radiation or infection." (PMID 40141336, 2025). "Compared with uninfected or ΔcagA-infected gastric mucosa, AQP5 expression enhanced remarkably in gastric mucosa after H. pylori WT infection." (PMID 35538066, 2022). "As reflected by dual luciferase reporter assay and RT-qPCR results, H. pylori WT infection augmented the luciferase activity and mRNA level of AQP5 promoter, whereas ASCL1 knockdown abrogated this trend." (PMID 35538066, 2022). "In the present study, we demonstrated that infection with the highly pathogenic avian influenza A/H5N1 virus stimulated the expressions of Sftpc and Aqp5+, and that administration of MSCs enhanced both of these expressions." (PMID 33176722, 2020). "Before infection, we confirmed that, although to a lesser extent compared to the whole salivary gland, SGACs expressed common markers of acinar cells, including aquaporin-5 (Aqp5) and amylase-1 (Amy1)." (PMID 31892128, 2019). "Our present study illustrated that, in a rat model of uncontrolled HS and infection, resuscitation with HES 130/0.4 significantly attenuated the HS-induced decreased expression of AQP1 and AQP5 in the lung tissues." (PMID 23741323, 2013). "As the gastric aquaporin Aqp5 is expressed on the lateral and intercellular membranes in the gastric crypts, we speculate that this pore is influenced by changes to tight junction proteins, and that it plays a role in the development of oedema in the epithelium during infection." (PMID 19317916, 2009). "RT-qPCR exhibited that AQP5 mRNA level increased in the gastric mucosa of H. pylori WT-infected mice and peaked at the 9th week of infection, whilst ΔcagA infection did not impact AQP5 levels in mouse gastric mucosa." (PMID 35538066, 2022). "The current experiment showed that in a rat two-hit model of hemorrhagic shock and infection, the decreased expressions of AQP1 and AQP5 may play an important role in acute lung injury." (PMID 23741323, 2013). "The fluid resuscitations with hydroxyethyl starch may be the better choice for preventing ALI after severe HS and infection, in part by up-regulating the expressions of AQP1 and AQP5." (PMID 23741323, 2013). "Therefore, it is considered that the protective effects of HES 130/0.4 on endothelial barrier dysfunction and high epithelial permeability after uncontrolled HS and infection, to some extent, in part by upregulating the expression of AQP1 and AQP5." (PMID 23741323, 2013). "Additionally, ASCL1 mRNA level increased in the gastric mucosa of H. pylori WT-infected mice and peaked at the 9th week of infection, but ΔcagA infection did not alter AQP5 expression in mouse gastric mucosa, which was validated in primary mouse GECs." (PMID 35538066, 2022).
benign tumor (6 papers, 2011 to 2024). "Our previous studies have identified that the expression level of AQP5 in malignant and borderline ovarian tumors is significant higher than those in benign tumors." (PMID 25298246, 2014). "Our previous studies have shown that the expression of AQP5 in malignant and borderline epithelial ovarian tumors is significantly higher than that in benign tumors and normal ovarian tissue." (PMID 25298246, 2014). "In benign tumor, AQP5 labeling was mainly seen at the apical domains of ductal epithelial cells." (PMID 22145049, 2011). "The expression of AQP1, AQP5 and AQP9 are significantly higher in malignant and borderline ovarian tumors than benign tumors and normal ovarian tissues." (PMID 24918928, 2014).
inflammation (4 papers, 2019 to 2024). Aberrant reaction of the microcirculation characterized by movement of fluid and leukocytes from the blood into extravascular tissues. "According to reports, AQP5 is down-regulated in lung inflammation, and up-regulation of AQP5 mitigates lung inflammation." (PMID 35324416, 2022).
adenocarcinoma (3 papers, 2013 to 2023). A common cancer characterized by the presence of malignant glandular cells. "Moreover, correlation analysis of Aqp5 and GSK-3β using Hscore indicated a statistically significant correlation between Aqp5 and GSK-3β in the overall samples and in the subset of IPMN with adenocarcinoma." (PMID 35646902, 2022).
blood cancer (1 paper, 2008). "Comprehensive functional studies to verify the novel oncogenic and anti-apoptotic properties of AQP5 in blood cancer are also warranted." (PMID 18612408, 2008). "Thus, in this study, we have pursued the role of AQP5 in CML as a first model to study the role of AQPs in blood cancer." (PMID 18612408, 2008).
cancers of the digestive system (1 paper, 2023). "High expression of AQP5 in cancers of the digestive system is linked to greater progression of the disease, resistance to chemotherapy, and worse prognosis." (PMID 36766810, 2023).
eye disorder (1 paper, 2024). A non-neoplastic or neoplastic disorder that affects the eye. "Ophthalmic agents used for eye disorders may also work, at least in part, by regulating AQP5." (PMID 38612559, 2024).
gastrointestinal disease (1 paper, 2022). A disease that occurs in the gastrointestinal system, excluding the hepatobiliary system. "However, the specific impact of AQP5 on the physiological function of gastrointestinal tract remains unknown, which is required to further investigated in the future to offer novel therapies to regulate fluid movement in gastrointestinal diseases." (PMID 35538066, 2022).
AQP5 also shares sentences with these, for which no sentence is quoted: allergic asthma (2 papers); bronchitis (2); congenital cataracts (2); depression (2); epithelial ovarian tumors (2); head and neck cancer (2); lung (2); metastasis (2); oral squamous cell carcinoma (2); acute pancreatitis (1); adrenocortical carcinoma (1); age-related macular degeneration (1); alcohol abuse (1); Alzheimer disease (1); asthenozoospermia (1); atrophic gastritis (1); Autoimmunity (1); bacterial infection (1); bacterial Sepsis (1); benign ovarian tumors (1); biliary tract cancer (1); brain tumor (1); breast tumors (1); celiac disease (1); cholangiocarcinoma (1); chronic lung disease (1); chronic rhinosinusitis (1); Cirrhosis (1); clear cell carcinomas (1); colon adenocarcinoma (1).
A further 39 diseases each share a sentence with AQP5 in 1 paper.